ENSG00000288635 (novel protein, readthrough ST7-OT4 - ST7)
Gene: Protein-coding gene on chromosome 7 (116,954,391 to 117,119,719, forward strand). Ensembl gene ENSG00000288635.
Genetic constraint (gnomAD): Loss-of-function variants: 1 observed, 7.88 expected, observed/expected ratio (o/e) 0.13, 90% interval 0.044 to 0.6. That is too few expected variants to judge how well the gene tolerates losing a copy. Missense variants: 57 observed, 96.44 expected, observed/expected ratio (o/e) 0.59, 90% interval 0.48 to 0.74. Synonymous variants: 41 observed, 38.11 expected, observed/expected ratio (o/e) 1.08, 90% interval 0.84 to 1.4.